CD34 (CD34 molecule)
Diseases named in the same sentence as CD34 in open-access papers (continued):
Sharing a sentence is not in itself a finding about the gene and the disease.
tumor (continued). "For the combinations, A + F liver showed negative reactivity for CD34 in cirrhotic nodules, and weak reactivity (+) in tumor nodules while S + F showed an opposite pattern with weak reactivity (+) for CD34 in cirrhotic nodules, and negative reactivity in tumor nodules." (PMID 36874031, 2023). "If the CD34+ cells engrafted into the immune-deficient mouse are autologous to the PDX, then one might expect the developing CD8+ T effector cells will be less likely to reject the tumor as a result of lack of HLA compatibility." (PMID 37509357, 2023). "However, CD34 expression or BRAFV600E mutation in GG may not impact the surgical prognosis of seizure outcome, as well as tumor PFS, if complete tumor resection could be achieved." (PMID 36910263, 2023). "Additionally, the observation that ERVE-4- and hERV47000-derived epitopes were able elicit a tumor-restricted CD8+ T-cell response were the basis for an ongoing phase 1 trial evaluating the safety and efficacy of the infusion of ERVE-4 TCR-transduced CD8+/CD34+-enriched T cells (NCT03354390)." (PMID 36979914, 2023). "On day 35 after tumor cell injection (prior to the disease-associated terminal end point), the animals were sacrificed, and analysis of the BMMs from mCh-AML–engrafted animals showed increased mCherry fluorescence compared with BMMs from control animals transplanted with nonmalignant CD34+ cells." (PMID 34990402, 2022). "However, CD34 expression or BRAFV600E mutation in GNT may not impact the surgical prognosis of seizure outcome, as well as tumor PFS if complete tumor resection was performed." (PMID 36307486, 2022). "Moreover, tumour cells in myxoid PTs were usually negative for CD34, which may suggest that the origin of this tumour is different from that of the other five types." (PMID 35906487, 2022). "Interestingly, we observed also 4PD binding to lineage negative CD34+ckit+ hematopoietic precursors in the bone marrow, spleen and tumor suggesting that this platform might be used to modulate gene expression on HSPCs." (PMID 35064009, 2022). "Besides, the conjugate showed a high antitumor effect in SGC-7901 tumor model with a tumor inhibition rate of 59.57%, and which might be mediated by increasing the levles of TNF-α, Bax and Caspase-3 and reducing the levels of CD34, VEGF, MMP-2, MMP-9 and Bcl-2." (PMID 36463199, 2022). "However, the spindle tumor component was diffusely strongly positive for vimentin and negative for AE1/AE3, whereas all the tumor cells were negative for neuroendocrine markers and other mesenchymal markers, such as desmin, SMA, myglobin, mygenin, S-100, DOG-1, CD34, CD117 and." (PMID 33761637, 2021). "The data reported herein are comparable with other reported tumor cell enrichment and purging systems, which are based on different principles such as immunomagnetic beads for either tumor cell removal by selective enrichment or negative depletion by selection of CD34+ cells." (PMID 34654486, 2021). "Corresponding fractions of PBPC and CD34+ cells collected into the center outlet were 29.1 ± 18.6% and 31.5 ± 32.7%, respectively, for the short chip (left), whereas considerably fewer non-tumor cells were collected into the center “tumor” cell outlet when using the long chip." (PMID 34654486, 2021). "Tumor cells may show positive expression for CD34 and ASMA but STAT6 is negative." (PMID 33879215, 2021). "However, CD34 is now established as a marker of several other non-hematopoietic cell types, including vascular endothelium present within newly forming vessels or those just trapped within tumor tissues." (PMID 32620162, 2020). "Since it is evident that CD34+ cells after UCBT do not generate neoplasia, the present study may represent an initial platform to learn how CD34+ cells are orchestrating their gene expression by combining tremendous expansion and, at the same time, avoiding transformation." (PMID 32492887, 2020).
tumor (continued). "Immunohistochemically, the tumor cells were positive for vimentin, epithelial membrane antigen, calponin, and were partially mild to moderate positive for estrogen receptor, but completely negative for S100 protein, glial fibrillary acidic protein, CD34, desmin, SMA and cytokeratin." (PMID 31915021, 2020). "Lapidot and colleagues found that only the population of leukaemic cells that were positive for CD34 and negative for CD38 (CD34+CD38−) could initiate leukaemic engraftment in immune-deficient mice, and that the frequency of these tumour-initiating cells was about one per million cancer cells." (PMID 29991569, 2018). "However, there were no areas of obvious positive staining in the tumor tissues of group D. The MVD values of each group were determined according to the CD34-MVD method and were 29.6 ± 4.2, 22.2 ± 3.2, 17.8 ± 3.0, and 7.2 ± 1.5 for groups A, B, C, and D, respectively." (PMID 29162156, 2017). "All 12 studies offered WHO grade data, 2 studies analyzed the correlation between CD34 and age and gender, 1 also studied the factor of tumor size, and the other studied the correlation between CD34 and tumor location, whether there was relapse or not, and it was not dependent on survival time." (PMID 26886640, 2016). "Immunohistochemical analysis of the protein revealed that its expression was mainly at arteriolar vessels in the lamina propria in healthy tissues, while in both tumor types its expression could not be detected, although they displayed positive immunostaining using anti-CD34 antibody." (PMID 26482785, 2015). "However, the tumor partly showed negative CD34 and a 20% proliferative index." (PMID 24443842, 2014). "However, the absence of D2-40 and CD34 in tumor cells could also be found in several previously reported cases." (PMID 24063649, 2013). "Look and colleagues found that decreased CTNNA1 expression in CD34+CD38-CD123+Lin- cells from high risk del(5q) associated MDS or AML patients was associated with methylation of the CTNNA1 promoter, but not with point mutations of the residual allele in primary tumor cells." (PMID 19240791, 2009). "Immunhistochemically, tumor cells were positive for glial fibrillary acidic protein (GFAP), CD34 V600E-mutant BRAF, and CD34, negative for R132H-mutant IDH1." (PMID 41340779, 2026). "Immunohistochemistry was vital in establishing the diagnosis, as the tumor cells were positive for SMA and negative for desmin, CD34, S100, and keratin, in line with the typical MPC immunophenotype." (PMID 40230760, 2025). "Gemcitabine inhibited the growth of both WT and PAK1KO tumours, but did not affect the expression of CD31 or CD34." (PMID 41294859, 2025). "In the absence of gemcitabine, PAK4KO did not affect the expression of CD31, CD34 or fibronectin, suggesting that PAK4KO did not affect the angiogenesis within the tumour in this xenograft SCID mouse model." (PMID 41228228, 2025). "Immunohistochemistry revealed that a few tumor cells exhibited focal nuclear positivity for β-catenin, focal positivity for SMA, and desmin positivity, as well as CD34 positivity in vessels, whereas they remained negative for CD117 and S-100 in tumor cells." (PMID 41181483, 2025). "In this case, the absence of DDIT3 rearrangement and focal expression of CD34 and S100 are consistent with previously reported findings in LLT, supporting its classification within this tumor spectrum." (PMID 41246635, 2025). "Immunohistochemical results showed that the tumor cells expressed Vimentin, SMA, Bcl-2, CD56, CD34, CD31, Ki-67, ERG, RB, INI-1, and SATB2, but were negative for SSTR2 and CK." (PMID 40406261, 2025). "Immunohistological examination showed that the tumor cells were positive for EMA and negative for cytokeratin AE1/AE3, p63, desmin, CD34, S100, GFAP, and SOX10." (PMID 40766037, 2025).
tumor (continued). "Immunohistochemical analysis showed that the tumor cells of inflammatory myofibroblastoma strongly expressed vimentin, partially expressed desmin and ALK, and showed no expression of CD34 and CD117." (PMID 40548121, 2025). "PAK1KD also suppressed tumour angiogenesis by reducing the expression of the endothelial marker CD31, not CD34." (PMID 41294859, 2025). "The IHC findings showed the spindle-shaped tumor cells that were positive for SMA, desmin, and negative for KIT, CD34 (data not shown)." (PMID 40625542, 2025). "Specifically, the tumor was negative for CD117, DOG1, and CD34, diffusely positive for α-SMA and h-caldesmon, and exhibited a high mitotic index." (PMID 41209937, 2025). "The tumor was negative for cytokeratin AE1/AE3, p63, desmin, CD34, S100, glial fibrillary acidic protein (GFAP), and SOX10." (PMID 40766037, 2025). "Whole tissue analysis thus indicates that Lin-CD34+DNAM-1brightCXCR4+ cells- but not conventional CD34+ precursors- enter and can be recovered in tumor tissue." (PMID 38390333, 2024). "Immunostains revealed the tumor cells to be positive for CD31, CD68, CD163, and CD34 (focal), whereas CD8 and CD 21 were negative." (PMID 38824259, 2024). "Tumor cells in case 3 of our study were positive to vimentin and CD99 but they were negative to S-100, desmin, HHF-35, SMA, CD31, CD34, STAT-6 and pan-cytokeratin (AE1/AE3)." (PMID 39462411, 2024). "Tumor cells were positive to vimentin and CD99, but negative to S-100, SMA, HHF-35, desmin, CD31, CD34, STAT-6 and pan-cytokeratin (AE1/AE3)." (PMID 39462411, 2024). "The pathology showed the tumor cells to be positive for cytokeratin (CK), Vimentin, EMA, CD34, cyclinD1, negative for CK8, CK19, CK20, SMA, Desmin, S-100, CD117, Dog-1, Hepar-1, SOX-10 and ALK, and Ki-67 approximately 50%, which confirmed the diagnosis of SHC." (PMID 38552058, 2024). "However, malignant SFTPs can be negative for CD34, which may be due to tumour differentiation." (PMID 39362048, 2024). "Tumor cells were negative with the wide-spectrum cytokeratin panel (HMW-CK, LMW-CK, CK8/18, CK7, CK20), and also negative for CD34, Myogenin, S100, CD117 (KIT), CD31, ALK1, and CD99." (PMID 39768800, 2024). "The tumor cells expressed CD99, synaptophysin, CD56, MUC4, and EMA (focal), but not AE1/AE3, S100, smooth muscle actin, desmin, CD34, chromogranin A, GFAP, NKX2-2, PAX7, and INSM1." (PMID 39249507, 2024). "Immunohistochemistry showed that tumor cells positively expressed vimentin, SMA, and Desmin usually, and CK, CD68, CD30 and ALK were partially expressed positively, while CD117 and CD34 were usually negative expressed." (PMID 39193013, 2024). "IHC examination revealed tumour cells positive for CK, P40, P63 and Vimentin and negative for CD31, CD34, S100 and HMB45." (PMID 39816396, 2024). "Immunohistochemically, the tumor cells tested positive for desmin, vimentin, SMA, and CD34 and negative for S-100 and CK." (PMID 38590660, 2024). "Immunohistochemical staining (IHC) was performed to determine lineage, however, tumor cells were negative for pan-keratin, p40, CDX2, HER2, S100, CD45, SOX10, CD34, synaptophysin, chromogranin A, myogenin, DOG1, KIT (CD117), CD30, and ALK." (PMID 38497146, 2024). "Immunohistochemical staining of the spindle and epithelioid cell tumor region revealed that the tumor was positive for CD117 and DOG1, but negative for smooth muscle actin (SMA), CD34, S-100, CD10, HMB45, and desmin." (PMID 38952545, 2024). "Although the tumor samples showed positive STAT6 expression, EMA and CD34 were found to be negative, and the proliferation index based on Ki67 was low." (PMID 38341593, 2024). "Immunohistochemically, tumor cells reveal positivity for GFAP only, while they are negative for MAP2, OLIG2, and CD34." (PMID 38544524, 2024).
tumor (continued). "Histopathology revealed a cellular tumor comprising tightly packed round to fusiform cells arranged around blood vessels with intervening thick collagen, positive for CD99, vimentin, BCL2, CD34, and STAT6 and negative for EMA, CK AE1/AE3, S100, TLE1, and SMA." (PMID 38606238, 2024). "IHC analysis indicated the tumour cells were positive for CD31, CD34 and ERG and negative for pan-cytokeratin." (PMID 37686662, 2023). "The tumour cells were diffusely positive for smooth muscle actin and GRM1 (in > 95% of the neoplastic cells), focally positive for CD34 and negative for S100 protein, desmin, cytokeratin AE1AE3 and ERG." (PMID 36810795, 2023). "Tumor cells in the epithelial and mesenchymal regions were negative for DOG-1, CD34, S-100, SOX-10, STAT 6, SMA, C-Kit, Calretinin, Syn, CgA, TTF-1, ER, and PR." (PMID 37658451, 2023). "Immunohistochemically, the tumor cells were positive for smooth muscle actin (SMA) and negative for cytokeratin, desmin, H-Caldesmon, CD34, S100, ALK, and β-catenin." (PMID 36741963, 2023). "The tumor cells expressed SATB2, Bcl-2, TLE1, SMARCB1, but not CK, EMA, CD34, SMA, Desmin, S-100, CD99, STAT6, MyoD1, Myogenin, and Ki-67 LI is about 10%." (PMID 37361584, 2023). "Normally, BSNS tumours show immunoreactivity for S100, SMA and sometimes desmin but demonstrate no reaction with CD34, STAT6, EMA and myogenin, which was also included in the report of all three cases presented." (PMID 38027532, 2023). "All tumours expressed typical endothelial markers CD31, ERG, and CD34 and were negative for pan-cytokeratin." (PMID 37686662, 2023). "The tumor was negative for pancytokeratin, CK5/6, p63, MART-1/MelanA, S100, Sox10, p40, CD34, and CD23." (PMID 38247725, 2023). "The tumour cells of all cases were positive for CD117 and DOG-1, while CD34 was absent in one case (case 2)." (PMID 36890498, 2023). "The tumor cells are positive for neuroendocrine markers, such as Syn, CgA and NSE; nevertheless, they are negative for HMB-45, Malen-A, CD34." (PMID 36800595, 2023). "Tumour cells in CMN are positive for vimentin, desmin and actin but negative for CD34 and epithelial markers, however diagnosis is primarily based on morphology." (PMID 37203959, 2023). "In each of the lesions, immunochemistry staining was positive for nuclear β-catenin in about 30% of the tumor, while it was negative for CD117, DOG1, S100, SM Actin, Desmin and CD34; proliferation index Ki 67 was < 5%." (PMID 35913675, 2023). "The tumour cells express SMA and vimentin; partially express desmin, CD34, CD68 and ALK; and do not express CK or S100." (PMID 36855132, 2023). "Postoperative IHC revealed that the tumor was positive for desmin, S100, and EMA and negative for MyoD1, myogenin, CKpan, CD34, SMA, SOX-10, HMB, and MelanA." (PMID 37233406, 2023). "The immunoreactivity for pan-keratin, vimentin, CD34 and PCNA was positive, but INI-1 was negative in the organoids similar to the original EPS tumor tissue and xenograft tumors." (PMID 35677170, 2022). "The immunoreactivity for pan-keratin, vimentin, CD34 and PCNA was positive, but INI-1 was negative in the ODX1 and ODX2 tumors similar to the original EPS tumor tissue." (PMID 35677170, 2022). "Immunohistochemically, the tumor cells were diffusely and strongly positive for ERG while negative for S100, α-SMA, CD34, and other vascular markers." (PMID 36591513, 2022).
tumor (continued). "In our case, the tumor presented with strongly positive STAT6 and CD34, moderately positive CD99, negative EMA and S-100 markers, mitoses <5/10 HPF, and absence of necrosis, suggesting the diagnosis of grade 1 SFT." (PMID 36060387, 2022). "We found that Pan-TRK, S-100, and CD34 were positive by IHC analysis, while SOX10 and desmin were negative in the tumor." (PMID 35572973, 2022). "Immunohistochemical staining showed that the tumor cells were positive for vimentin and Bcl-2 but negative for S-100, desmin Syn, WT-1, EMA, CD34, and CD99; the Ki-67 index in tumor cells was 40%." (PMID 36482604, 2022). "While tumor angiogenesis was still observed in Nrp1 knockout models, there was a lack of VEGF-mediated proliferation and no increase in CD34+ CSC population." (PMID 36203599, 2022). "Immunohistochemical stains showed the tumor cells to be positive for CD117, CD34 and CD10 and negative for ER, PR, CK7, PAX-8, pan-cytokeratin, EMA, S100, Melan-A, HMB45, SMA and CAIX." (PMID 36312876, 2022). "Immunohistochemistry showed that the tumor cells were focally positive for CD99 and BCL-2 and negative for CD34, S100, desmin, and myogenin." (PMID 35797605, 2022). "Mitotic activity was low, and the tumor showed diffuse expression of α-SMA, desmin, caldesmon, and calponin, without expression of myogenin, MyoD1, CD34, EMA or PS100." (PMID 36421692, 2022). "To this end, we first detect expression of two classic markers for angiogenesis, CD34 and VEGF, in tumor tissues formed from MDA-MB-231 cells with or without MIIP overexpression." (PMID 36130933, 2022). "Morphology and immunohistochemical stains were helpful to confirm the lymphatic nature of the tumor (the tumor cells were positive for CD31, CD34, and factor VIII, while negative for PanCK)." (PMID 35001360, 2022). "Immunohistochemical analysis revealed that CD34, c-kit and discovered on GIST (DOG)-1 were diffusely positive in tumor cells and alfa-SMA, desmin and S-100 were negative." (PMID 35666331, 2022). "Immunohistochemical findings of the resected specimen showed that the tumor cells were positive for c-kit, DOG-1 and CD34 and negative for smooth muscle actin and S100." (PMID 35666331, 2022). "Immunohistochemically, the tumor cells were positive for CD117, vimentin, CD56 and NSE and focally expressed desmin; the cells were negative for myogenin, S-100, SYN, INSM1, CD34, STAT6, INI-1, Brachyury, ERG, TLE1, AE1/AE3, WT-1, CD99 and SMA." (PMID 35488288, 2022). "Flow cytometry analysis showed the cells isolated from tumor tissues were all positive for CD73, CD90 and CD166, and negative for hematopoietic markers of CD14, CD19, CD34, CD45 and HLA-DR." (PMID 33744858, 2021). "It must be noted that CD34 and CD45 are markers for hematopoietic cells in general and do not allow for differentiation according to immune cell type and that tumor growth was not measured volumetrically." (PMID 33530441, 2021). "In IHC examinations performed for differential diagnosis, while vimentin, smooth muscle actin, myoglobin, and positive reaction in tumor cells are expected, a negative result is obtained with factor VIII-related antigen, epithelial membrane antigen, and CD34." (PMID 33355800, 2021). "Immunohistochemically, the tumor cells were negative for CD20, CD79a, CD3, CD5, c-kit, CD34, and TdT and positive for myeloperoxidase, CD33, CD68, and CD163." (PMID 34970464, 2021). "The tumor cells were negative for CD117, DOG1, CD34, S100, β-catenin, STAT-6, and ALK that played important roles in differential diagnosis." (PMID 34516510, 2021). "IHC analyses revealed that the tumor cells were positive for EMA and CD34 and negative for claudin-1, GLUT1, S100 protein, MUC4, STAT6, SMA, HMB45 and P16." (PMID 34592995, 2021).